CXCL9 (C-X-C motif chemokine ligand 9)
Diseases named in the same sentence as CXCL9 in open-access papers (continued):
Sharing a sentence is not in itself a finding about the gene and the disease.
tumor (continued). "Chemokines such as CXCL9 and CXCL10 can orchestrate the migration of effector CXCR3+ immune cells such as Th1 cells into the tumor sites, subsequently shaping both the tumor immunity and therapeutic responses." (PMID 31991604, 2020). "Recent evidence in T cell-inflamed tumors highlights the key role of CD103+ DCs in the baseline CD8+ CTL-mediated immune response against tumor antigens, and their presence in the TME of human tumors correlates with the secretion of CXCL9/10." (PMID 33171765, 2020). "CD8A, DOK2, CX3CR1, TYROBP, CXCL9, CD300LF, and IFNG were identified as significant DEGs between tumor samples with high and low CD200R1 expression." (PMID 32635224, 2020). "In our study, the expression of CXCL9 in HNSCC tissues increased significantly when compared with non-tumor tissue, and the expression was also markedly related to tumor stage in patients with HNSCC." (PMID 33489879, 2020). "Treatment with CEA-TCB triggered secretion of pro-inflammatory cytokines (IFNγ, TNFα, IL-2) and several chemotactic molecules (CXCL9, CXCL10, CXCL11, CXCL13) indicating the generation of a highly inflamed tumor microenvironment." (PMID 33330050, 2020). "Immune cells show anti‐tumour effect against cancer cells through paracrine CXCL9, CXCL11/CXCR3 axis in tumour models." (PMID 32820615, 2020). "The CXCR3 ligands CXCL9, CXCL10 and CXCL11 were all elevated in the tumour, suggesting that the CXCL9/CXCL10/CXCL11–CXCR3 axis is involved in both CD4+ and CD8+ T cell infiltration into the tumour." (PMID 32439888, 2020). "We also probed for myeloid cells expressing CXCR3 (the receptor for CXCL9-11) and CCR2 (one of the receptors for CCL11 and uniquely a receptor for MCP1) within our tumor digests." (PMID 31940491, 2020). "Mature DCs can also secrete cytokines to foster T cell response and release chemokines such as CXCL9, CXCL10, CCL3, CCL4, and CCL17 to recruit T cells into the tumor bed." (PMID 33505304, 2020). "CXCL9 and CXCL10 were reported to promote tumor suppression by increasing immune cell differentiation, migration, and activation." (PMID 33323542, 2020). "Meanwhile, CXCL9, CXCL10 and CXCL11, chemokine ligands for CXCR3, were expressed at high levels in the tumours, thus attracting CXCR3+CD8+ T cells." (PMID 32439888, 2020). "On the other hand, CXCL9 and CXCL11, secreted by M1 macrophages, promote a Th1-type response and stimulate tumor-infiltrating cytotoxic T cells." (PMID 33238581, 2020). "In this study, it was found that tumor-derived CCL5 has recruited effector T cells to tumors; the release of IFNγ by T cells has increased the production of CXCL9 by macrophages, leading to increased immune surveillance of the tumors." (PMID 32582148, 2020). "Currently much attention is given to CXCL9 and CXCL10 and their role in the potentiation of anti-tumor CD8+ T cells." (PMID 32547545, 2020). "One of these mechanisms can likely be attributed to increased Cxcl9 expression in LLC-sh21 tumors, which we detected by message in tumor sections." (PMID 31133614, 2019). "This study demonstrated a positive correlation of CXCL9, CXCL10, and CXCL11 mRNA expression with the density of tumor-infiltrating T and NK cells." (PMID 30873179, 2019). "So far, our data indicated that the inhibition of LIF induced a change in the phenotype of TAMs increasing the expression of CXCL9 and leading to the recruitment of CD8+ T cells to the tumor." (PMID 31186412, 2019). "On the other hand, other reports showed that chemokine ligands including CXCL9 and CXCL10 have potential angiostatic and anti-tumor activities." (PMID 31620367, 2019). "We found ten potential prognostic genes, including eight tumor suppressor and/or driver genes (VEGFA, CCND1, BAX, IL7R, SHC1, FLT1, IL7, and JAK3), as well as two chemokines (CXCL9 and CXCL10)." (PMID 31661791, 2019). "Eight potential classifiers were studied including CR, clinical stage of tumor at the time of diagnosis, CD8 density, PDL-1 status, CXCL9, IDO1, LAG3, and TIM3." (PMID 31360303, 2019).
tumor (continued). "CD8+ T-cell tumor infiltration and tumoral gene expression of IFNG, CD8A, CXCL9, and granzyme K (GZMK) were also increased following MEDI0680 administration." (PMID 31439037, 2019). "It has been found that CXCR3-binding chemokines (such as CXCL9 and CXCL10) are critical and essential for the recruitment of activated CD8+ T cells to tumor sites." (PMID 31616443, 2019). "Other research demonstrated that the use of DPP4, which inhibits CXCL9/CXCL10 processing intratumourally, increased cDC1 infiltration into B16F10 murine melanoma tumours." (PMID 31091774, 2019). "CXCL9 and CCL2 stood out as chemokines described to be critical for CD8+ T cell tumor infiltration, and the recruitment of TAMs and Tregs15–17, respectively." (PMID 31186412, 2019). "Conversely, consistent with the angiostatic effects of CXCL9 and CXCL10 by binding to their receptor CXCR338, we earlier reported reduced angiogenesis in LLC tumors from Cav-2 KO mice as early as day 6 after tumor cell implantation." (PMID 31831780, 2019). "Treatment with anti-LIF increased CXCL9 and decreased CCL2 expression, while inducing immune cell infiltration into the Matrigel surrounding the tumor specimen." (PMID 31186412, 2019). "CXCL9 has been produced by murine cDC1 in a tumor model, recruiting CD8 T cells within the tumor microenvironment." (PMID 30764500, 2019). "Gene expression analyses performed on CD11b+ tumor infiltrating immune cells isolated from EONY#17 tumors showed enhanced expression of the M1-like markers IL1β, Cxcl9, IL6 and Nos2." (PMID 31519152, 2019). "We found that the levels of CXCL9 and CXCL11 were significantly increased in both cell medium of irradiated EG7-OVA cells and the supernatants derived from MC38-OVA tumor tissues after irradiation." (PMID 31921127, 2019). "IL-17 signaling also inhibits the production of T cell attracting chemokines CXCL9 and CXCL10 by tumor cells." (PMID 31775909, 2019). "CXCR3 is essential for T cell recruitment into tumors and through the thymus and Th1 cells also produce IFNγ that induces additional production of CXCL9 and 10 to enhance the recruitment of cytotoxic CD8+ T cells into the tumor." (PMID 30873179, 2019). "Loss of IL-17 signaling also increased the expression of CXCR3, the cognate receptor for CXCL9/10/11 chemokines, likely reflecting an increased recruitment of CXCR3-expressing lymphocytes to the tumor." (PMID 31775909, 2019). "Herein, we found that 5 genes (Shisa3, PADI1, LRP2, ANGPTL4 and ALOX15B) were upregulated and 4 genes (CXCL9, ADAMDEC1, SCGB1A1/CC10, HLA-G) were downregulated in PR tumor tissues compared to SD tumor tissues." (PMID 31801598, 2019). "These regressing tumors showed a higher prevalence of CXCL9 in the TME compared with conventional tumors and exhibited an increased presence of TIL and tumor necrosis rate." (PMID 31216755, 2019). "However, the average expression of CXCL10 and CXCL9 was higher in Group 2 tumors by 22.8-fold and 12.3-fold, respectively, which supports the idea that Group 2 tumors were “immune-active”, which may have resulted in a PD-1 positive tumor immune environment." (PMID 31618954, 2019). "Tumor infiltrating cDC1s are also the main producers of different chemokines, including CXCL9 and CXCL10, which help to promote the recruitment of CD8+ T cells into the tumor microenvironment (TME)." (PMID 31736936, 2019). "In this study, we found that the expression of CCL5, CXCL9, and CXCL11 was increased in tumor cells after irradiation." (PMID 31921127, 2019). "Since IFN-I is known to induce the expression of lymphocyte-recruiting chemokines such as CXCL9, CXCL10, and CXCL11, we measured the mRNA expression level of these chemokines in the tumor-containing lungs at 21 d.p.i." (PMID 31049360, 2019). "TSCC cell show an increased CXCL9 and CXCR3 expression, which results in cytoskeleton alterations and decreased cell adhesion molecules that promotes tumor cell invasion and migration to the lymph nodes." (PMID 31216755, 2019).
tumor (continued). "CXCR3, the receptor of chemokine CXCL9, is frequently upregulated in HCC and correlates with tumor size, tumor differentiation, portal invasion, and metastasis." (PMID 31623313, 2019). "LIF establishes a cross-talk between the innate and the adaptive immune response since LIF neutralization regulates the expression of a chemokine program in TAMs, including CXCL9, leading to an increase in CD8+ T cell tumor infiltration." (PMID 31186412, 2019). "The data showed that there were significantly more IFN-γ, Granzyme B, perforin, Th1-type chemokine CXCL9, and less TGF-β and angiogenesis markers (CD105 and VEGF) in tumours receiving vvDD-IL-2-RG treatment, compared with other virus treatments." (PMID 30410056, 2018). "Endothelial cells in human specimen were able to produce CXCL9 and CXCL10 in both unaffected tissue and tumor, confirming an endothelial origin of these chemokines in both species." (PMID 29671006, 2018). "IFNγ produced within the TME induces CXCL9, CXCL10, and CXCL11 expression, which correlates with tumor infiltrating CTL and Th1-effector cells and with a positive survival rate in colorectal cancer." (PMID 30319638, 2018). "EZH2-mediated H3K27me3 and DNMT1-mediated DNA methylation repress the tumor production of T helper 1 (Th1)-type chemokines CXCL9 and CXCL10, and subsequently determine effector T-cell trafficking to the tumor microenvironment." (PMID 29556394, 2018). "Metastasis can be promoted by endothelial cell secretion of CXCL9 (and CXCL10), assisted by VEGF, within the tumor microenvironment or autocrine CXCL10/CXCR3 interactions on tumor cells." (PMID 30320116, 2018). "Anti-tumor immunity within the TME can be supported by immune-stimulatory cytokines, such as CXCL9 and CXCL10, involved in the recruitment of immunological infiltrates at tumor site." (PMID 30581389, 2018). "In vitro, the chemokines increased after radiotherapy in the parental tumor cell, and CCL2-5, CXCL9, CXCL10, CXCL16 were much higher than in the resistant cell." (PMID 30093664, 2018). "Efficient NK–DC interaction in the tumor can lead to increase of CXCR3 and CCR5 on DC, which can recruit CD8+ effector T cells to tumors, in the presence of chemokines CXCL9, CXCL10, and CCL5." (PMID 30200478, 2018). "The expression levels of CXCL9 and CXCL10 also tend to be lower in the affected skin of patients with MF during the tumor stage than during the patch and plaque stages." (PMID 29915722, 2018). "In this work, it was shown that CXCL9 and CXCL12 are co-expressed in the perivascular area of the tumor, and can form a complex enhancing CXCR4-mediated recruitment of tumor-infiltrating lymphocytes and malignant B cells." (PMID 30319638, 2018). "In the early stages of MF, expression of CXCL9, CXCL10, and CXCR3 is believed to be important for recruitment and accumulation of tumor cells in the skin." (PMID 29915722, 2018). "Inhibition EZH2 in colorectal cancer cells augmented CXCL9 and CXCL10 expression to affect the infiltration of effector T cells in tumor." (PMID 29556394, 2018). "Galectin antagonists increase intratumoral IFNγ diffusion, CXCL9 gradient and tumor recruitment of adoptively transferred human CD8+ T cells specific for a tumor antigen." (PMID 28986561, 2017). "Of note, expression of CCL5 was significantly higher in tumours of artLCMV-OVA-treated animals than in those receiving rLCMV-OVA or rAd-OVA (similar trend for Cxcl9)." (PMID 28548102, 2017). "Among these, CXCL9 and CXCL10 stand out as their tumor expression correlates with prolonged disease-free survival of patients with colorectal carcinoma and other cancers." (PMID 28986561, 2017). "Double-immunofluorescence staining showed chemokine expression (CXCL9, CXCL10 and GRO) in the tumour cell cytoplasm/nucleus and deposited in the extracellular matrix." (PMID 28386296, 2017).
tumor (continued). "Recently, studies have shown that CD103+ CD11c+ DCs, a subpopulation of dermal- and gut-resident pAPCs, respond to tumor-derived CCL4 and are the chief cells that produce CXCL9 and CXCL10 to recruit tumor-infiltrating T cells." (PMID 29109732, 2017). "Employing this approach, they recognized a core of nine cytokines that consistently correlated with efficacious tumour suppression: IL-12p70, IFN-γ, IL-1α, IL-1β, IL-2, IL-3, IL-6, CXCL10, and CXCL9." (PMID 29089667, 2017). "Nevertheless, the capacity to recruit immune cells such as regulatory T cells also implies that CXCL9, CXCL10, and CXCL11 can shape the microenvironment toward a rather tumor-promoting milieu." (PMID 29379506, 2017). "CXCL9 and CCL5 can directly promote tumor growth but the cytokines are also a chemo-attractant which promotes T cell and monocyte infiltration into the tumor microenvironment and the development of T memory cells." (PMID 29137331, 2017). "Considering chemotactic factors, the mRNA expression of CCL5, CXCL9, CXCL16, and CCL25 was higher in HCCLM3 cells from micrometastatic regions than in cells from primary tumor sites when cocultured with MSCs." (PMID 28205428, 2017). "The upregulation of Ifng and Cxcl9 by anti-CD27, and combination therapy, indicate that these treatments polarize the macrophages toward an anti-tumor phenotype." (PMID 29198913, 2017). "Our data indicate that the tumor ECM has an essential role in the retention of IFNγ by galectin-3, as collagenase D treatment resulted in increased IFNγ availability and CXCL9 gradient formation." (PMID 28986561, 2017). "The expression of cytokine epidermal growth factor, CXCL9, CCL25, and MMP9 were differently expressed between primary tumor and metastasis sites, especially when cocultured with MSCs, suggesting a crosstalk between MSCs and tumor cells." (PMID 28205428, 2017). "The expression of epidermal growth factor, CXCL9, CCL25, and matrix metalloproteinases‐9 by HCC cells differed between primary tumor sites and metastatic regions." (PMID 28205428, 2017). "High number of tumor infiltrating lymphocytes correlate with increased expression of a cluster of chemokines that comprise CCL2 and CXCL10, with CXCL9 and CXCL10 critically involved in the recruitment of effector CD8+ T cells." (PMID 29064427, 2017). "In 20 Ewing sarcoma patients, Berghuis reported that CXCL9, CXCL10, and CCL5 that is highly expressed by tumor and stromal cells were correlated positively with accumulated CD8+ T cells." (PMID 27726306, 2016). "Therefore, it may be speculated that CXCL9 plays a potential role in tumor TEM." (PMID 27738495, 2016). "Noteworthy, it was recently reported that epigenetic modulation of CXCL9 and CXCL10 promoted tumor T cell infiltration and enhanced efficacy of PD-L1 blockade." (PMID 27343548, 2016). "A similar effect of EZH2 was observed in colorectal cancer, where targeting EZH2 in cancer cells also augmented the expression of CXCL9 and CXCL10 chemokines, affecting the infiltration of the tumor by effector T cells." (PMID 27793053, 2016). "A similar effect of EZH2 was observed in colorectal cancer, where targeting EZH2 in cancer cells augments the expression of CXCL9 and CXCL10 chemokines affecting the infiltration of the tumor by effector T cells." (PMID 27199994, 2016). "Chemokines CXCL9, 10, and 11 signal via their common receptor CXCR3 and thereby recruit lymphocytes to inflammation sites and enable their penetration into the tumor tissues." (PMID 28123870, 2016). "We found CXCL9 and CXCL10 expressing on tumor cells and stromal cells, and CXCL11 expressing strongly on stromal cells and weakly on tumor cells." (PMID 26910919, 2016). "To illustrate how the chemokine CXCL9 and its receptor influence the cell invasion, we screen the MAPK signaling which is of great importance on tumor metastasis, including the four main pathway ERK1/2, AKT, P38MAPK, JNK." (PMID 26883105, 2016).
tumor (continued). "In murine tumor models, IL21 induces a Th1 immune response and anti-angiogenic effects mediated by CXCL9 and CXCL10." (PMID 26305332, 2015). "We further detected the expression of IFN-γ and CXCL9 in tumor site, and found that IFN-γ and CXCL9 were significantly up-regulated in the tumor tissues of the ApcMin/+;CD11b−/− mice compared with the ApcMin/+ mice." (PMID 26526388, 2015). "Although expression of CCL5, CXCL9, CXCL10 and CXCL12 were also consistently detected in the tumours, expression of each was also detected in spleen and lymph node." (PMID 25495686, 2015). "These suggest that CXCL9 and CXCL10 are also the major chemokines that guide the adoptively transferred OT-I cells to the treated tumor." (PMID 25460506, 2015). "The myeloid cells also secrete cytokines, which promote MDSC recruitment to the tumor sites, further induce IFN-γ and CXCL9 production and activate Wnt/β-catenin signaling in CRC." (PMID 26526388, 2015). "The expression of genes in tumours was low for CD3Z, CD8, CXCL13, SNAI2 and ESR1 (40-DCq <32) and moderate for IGHM, CD4, CXCL9 and FOXP3 (40-DCq 32–35)." (PMID 25970543, 2015). "Tumor-free induction by PMSB were mostly reversed by IFN-γ or IP-10/CXCL10 blockade and evidently deterred by MIG/CXCL9 or RANTES/CCL5 blockade (P < 0.05 versus controls)." (PMID 26512920, 2015). "CXCL9, CXCL10, CXCL12 and FSP1 production by CAFs promote recruitment of T lymphocytes into the tumor; however the number of cytotoxic T cells versus tumor suppressive cells is shifted." (PMID 24978438, 2014). "In breast cancer, NK cells take advantage of their own production of IFN-γ to enhance the secretion of chemokines CXCL9, CXCL10, and CXCL11 by tumor cells, which in turn accelerate the infiltration of CXCR3 expressing NK cells into the tumor site." (PMID 25110692, 2014). "With respect to angiogenesis, IFN-γ is a potent inducer of several angiostatic chemokines, such as CXCL9 and CXCL10, from a variety of cells, including monocytes, macrophages, fibroblasts, endothelial cells, and tumor cells." (PMID 23533029, 2013). "The correlation between CXCL9 serum levels and EBV DNA load was also analyzed to clarify its relationship with the NPC tumor burden." (PMID 24278236, 2013). "Whereas in tumor-bearing mice groups, most of cytokines were decreased after LF-MF exposure, including KC, CCL1, IFN-γ, CXCL9, CXCL12, TREM-1, CCL12, IL-1rα and IL-16." (PMID 24314291, 2013). "However, other studies showed that CXCL9 expression also could be seen during active tumor growth." (PMID 24278236, 2013). "Although CXCR3 is expressed in cytotoxic T cells, several studies demonstrated that CXCL9 and CXCL10 induced migration of CXCR3+ tumor cells, suggesting that CXCR3+ tumor cells preferentially metastasize to lymph nodes expressing these ligands." (PMID 24213462, 2012). "The anti-angiogenic (CXCL9, CXCL10) and pro-angiogenic markers (VEGFa, CXCL2, CXCL5, Angiopoietin 1 and Angiopoietin 2) were quantified in the tumor by RTQPCR." (PMID 22815789, 2012). "Chemokines that are found in the tumour environment, produced mainly by activated macrophages, are the CXCR3 ligands CXCL9/MIG and CXCL10/IP-10, attracting CXCR3-expressing T-cells and natural killer cells." (PMID 21179030, 2011). "Intrahepatic lymphocytes, isolated from non-tumor tissue, were stimulated with peptides overnight and culture supernatants were screened for CXCL-8, CXCL-9, CXCL-10, CCL-5, CCL-2 as well as IL-17 and the anti-inflammatory cytokine IL-10." (PMID 21876747, 2011). "Several cytokine mRNAs' (CCL3/MIP-1α, CCL15/MIP-1δ, CXCL1, CXCL5/ENA78, CXCL8/IL8, CXCL9/MIG, CXCL10/IP10) were found to be overexpressed in the tumours while CCL15/MIP-1δ, CXCL5/ENA78 and IL8 mRNAs' were overexpressed in paired normals, as well." (PMID 21092330, 2010).